ZNF496-DT (ZNF496 divergent transcript)
Synonyms: XLOC_000647
Gene: Long non-coding RNA gene on chromosome 1 (247,332,054 to 247,393,948, forward strand). Ensembl gene ENSG00000289234.
Diseases named in the same sentence as ZNF496-DT in open-access papers:
ZNF496-DT is named in the same sentence as 1 disease in open-access papers, as found by Europe PMC text mining. Sharing a sentence is not in itself a finding about the gene and the disease.
ZNF496-DT shares sentences with these, for which no sentence is quoted: tumor (1 paper).